BRCA1 (BRCA1 DNA repair associated)
Diseases named in the same sentence as BRCA1 in open-access papers (continued):
Sharing a sentence is not in itself a finding about the gene and the disease.
breast cancer (continued). "The cell lines chosen for analyzing anti-survival effects of these drugs represented the clinically relevant subtypes of breast cancer, i.e., non-TNBC with luminal and HER2+ breast cancer cells as well as TNBC without and with BRCA1 mutation." (PMID 34356606, 2021). "This is consistent with previous reports in breast cancer and cell line experiments where Signature 3 was only detected for BRCA1/2, PALB2 and RAD51C genes but not ATM or CHEK2." (PMID 33917078, 2021). "We also have analyzed 60 breast cancer samples by immunohistochemistry (IHC) and found FGFR2 is negatively correlated with YY1 and BRCA1, suggesting that YY1 could be responsible for BRCA1 reduction in response to FGFR2 activation." (PMID 34514747, 2021). "Alteration of KLF4 levels could be a good strategy to promote the efficacy of olaparib in killing breast cancer cells, especially for the population of TNBC patients who have normal BRCA1 function." (PMID 33231937, 2020). "Inherited genetic risk factors such as BRCA1 and BRCA2 mutations are observed more often among breast cancer patients, but are not the sole causal factors." (PMID 32731431, 2020). "With regard to male breast cancer, routine screening is not recommended for BRCA1, while for BRCA2 annual clinical exam can be considered starting from age 40 onwards." (PMID 32655641, 2020). "The decrease of the poly-ubiquitylated forms of Bcl-2 in cells depleted of BRCA1, independently of PRMT1 expression, also confirmed that cytosolic BRCA1 might control the stability of Bcl-2 in breast cancer cells." (PMID 32764667, 2020). "Currently there are no studies addressing the impact of obesity on BRCA1-related breast cancer development." (PMID 32785175, 2020). "To this aim, we selected four breast cancer cell lines of TNBC, including the BRCA1 mutant cell line MDA-MB-436 (basal-like), and the BRCA1 wild type lines with BRCA1 allelic loss but normal transcript levels MDA-MB-468 (basal-like), MDA-MB-231 (claudin-low) and MDA-MB-453 (LAR-subtype)." (PMID 32903519, 2020). "A total of 302 BRCA1 and BRCA2 negative index breast cancer patients were screened for RECQL germline variants." (PMID 33342430, 2020). "In contrast, nontreated patients with BRCA1 methylation, compared with nontreated patients without BRCA1 methylated tumors, showed similar time to breast cancer–specific death." (PMID 32175521, 2020). "Synthetic lethality has also be reported with other HR related proteins including BRCA1, PALB2, FAM175A (ABRAXAS), and BARD1 in breast cancer cells where a more specific PARGi, PDD00017273, was used and on-target effects validated using two independent PARG siRNA." (PMID 33005627, 2020). "Within breast cancers, TMB was higher for BRCA1 and BRCA2 germline mutation carriers relative to non-carriers and was also elevated in BL1 subtype." (PMID 32164626, 2020). "However, most ovarian and breast cancers, and nearly all other types of cancer, have normal BRCA1 and BRCA2; and even in BRCA1/2-mutant tumors, responses to PARPi are heterogeneous and initially responsive cancers eventually develop PARPi resistance." (PMID 32029902, 2020). "The presence of active PRMT1 favored the formation of BRCA1 foci after IR, whereas the absence of this methylase induced the accumulation of 53BP1 foci in breast cancer cells." (PMID 32764667, 2020). "For example, in mice, inactivation of the Bard1 protein induces mammary tumors that are indistinguishable from tumors that result from Brca1 knock-out." (PMID 32997669, 2020). "Due to her personal and family history, positive for premenopausal breast cancer, the patient’s mother had previously undergone a comprehensive BRCA1/BRCA2 molecular analysis, which resulted negative." (PMID 32899294, 2020).
breast cancer (continued). "BRCA1 and BRCA2 breast cancer patients’ fertility were compared to non-BRCA-mutated women with breast cancer and to healthy controls." (PMID 31872386, 2020). "The most important reason for this is that MRI is not affected by breast density and BRCA1 and BRCA2 mutation carriers are associated with a diagnosis of breast cancer at a young age, resulting in dense breasts." (PMID 31734900, 2020). "In summary, we demonstrate that BRCA1 methylation is an important predictive factor of chemosensitivity in breast cancer rather than being a prognostic factor." (PMID 32175521, 2020). "In addition, further study towards the relationship between ENC1 and breast cancer cell special molecular such as HER2 and BRCA1 is essential." (PMID 32618411, 2020). "Initial clinical testing (BRCA1, BRCA2 and PALB2) in a 40-year-old female with unilateral breast cancer did not detect any pathogenic variants." (PMID 32884827, 2020). "In contrast, some evaluations concluded that BRCA1 is not part of NHEJ pathway in BRCA-deficient HCC1973 cell lines using pulsed-field gel electrophoresis and further showed sporadic breast cancer cells has intact NHEJ activity in DSB repairing." (PMID 33013205, 2020). "BRCA1 and BRCA2 mutated breast cancers have been reported to have different molecular characteristics from each other, for example, a correlation between TNBC and BRCA1 but not BRCA2." (PMID 32455662, 2020). "Since PRMT1, through BRCA1 methylation, controls the localization of BRCA1, we next examined whether PRMT1 protects breast cancer cells from IR-induced apoptosis." (PMID 32764667, 2020). "Unlike BRCA1 mutation carriers, the pathological feature of breast cancer patients with a BRCA2 mutation is usually similar to sporadic breast cancer." (PMID 33013205, 2020). "The risk of breast cancer in c.156_157insAlu BRCA2 mutation carriers does not differ from that of other BRCA2 and BRCA1 pathogenic mutation carriers, this is supported by cumulative evidences." (PMID 32070378, 2020). "Moreover, under BRCA1-defective conditions, NOTCH1 tended to display an enhanced ability to promote TNBC and basal-type breast cancer." (PMID 32591500, 2020). "The data suggest that maintaining normal glucose levels supports BRCA1 function in restraining IGF-I lipogenic actions and that this may slow breast cancer progression." (PMID 33212987, 2020). "Currently, both the National Comprehensive Cancer Network (NCCN) guidelines and European Society for Medical Oncology (ESMO) guidelines recommend genetic testing for BRCA1 and BRCA2 for women with multiple primary breast cancers, if first diagnosis was ≤50 years old." (PMID 32854451, 2020). "Here, we show that SIRT4 possesses its tumor-suppressive effect on breast cancer by inhibiting glutamine metabolism and thereby affecting the protein levels of SIRT1, which modulates the acetylation patterns of histones H4 and regulates stemness via BRCA1." (PMID 32863939, 2020). "We first separated breast cancer samples into two groups based on estrogen receptor (ER) expression status (positive or negative) and ranked the samples in each group based on BRCA1 expression levels." (PMID 32139898, 2020). "Internationally, only a few studies have explored decision support for BRCA1/2-positive women without breast cancer." (PMID 32513307, 2020). "The BRCA1 and BRCA2 mutation carriers have a 6–12 times higher lifetime risk of developing breast cancer compared to non-carriers." (PMID 31734900, 2020).
breast cancer (continued). "There were 133 deaths related to breast cancer: 101 non-carriers, 19 BRCA1 carriers, and 13 BRCA2 carriers." (PMID 32341426, 2020). "We did not observe any survival benefit in BRCA1/BRCA2 carriers with HER-2 positive or ER/PR-positive HER-2 negative breast cancers (non-TNBC)." (PMID 32341426, 2020). "According to a case–control study in 1380 matched pairs of women with BRCA1 and BRCA2 mutations, there is no adverse effect of fertility treatment on the risk for developing breast cancer, compared with controls." (PMID 32070378, 2020). "(D) Box-plots of HR (BRCA1, BRCA2, ATR) and NHEJ (PRKDC, XRCC5, XRCC6) protein expression levels (ratio to pool) in the different groups of breast cancer cell lines according to AZD1775 response characteristics (recovering-basal, sensitive-basal and recovering-luminal)." (PMID 32628111, 2020). "This is because RHAMM, working in concert with BRCA1 and BRAC2, can significantly promote tumor growth and metastasis for pancreatic cancer in vivo, and multiple other cancer types such as basal-like breast cancer and glioma in vivo." (PMID 32241274, 2020). "In the case of breast cancer, the most promising gene seams to be HYAL1 while BRCA1 and 2 could be considered for further testing in different groups in order to test if it depends on the HER2 or RP status of the patient." (PMID 32610620, 2020). "About 10.41% of patients, who had no family history of having breast cancer or other BRCA1-related cancers among their 1st-degree relatives, and about 33.33% of patients, who had comorbidities, were found to have mutations." (PMID 32856854, 2020). "There are no controlled studies concerning the changes in BRCA1 subcellular localization and function in different breast cancer types." (PMID 33817238, 2020). "Herein, we only analyzed the prognostic value of these genes for the whole breast cancer due to lack of adequate BRCA1/2-mutant cases for accurate survival analysis, which was an undeniable limitation in our study." (PMID 31998560, 2020). "Furthermore, PARP inhibitors reduce rDNA transcription and ribosome biogenesis in BRCA1/2-proficient cancer cells by preventing DDX21 ADP-ribosylation, and thereby reduce breast cancer growth." (PMID 32029455, 2020). "She underwent BRCA1 and BRCA2 testing because her mother had a history of breast cancer." (PMID 32455662, 2020). "Amplification of RANK-expressing mammary duct progenitor cells can be found in the non-tumor breast tissue of BRCA1 mutant carriers, and these cells have similar molecular characteristics as basal-like breast cancer cells." (PMID 32850393, 2020). "The absence of BRCA locus-specific loss of heterozygosity in germline BRCA1 and BRCA2 carriers is another potential mechanism of primary resistance, even if the topic is debated and evidences on breast cancer are still lacking." (PMID 32471249, 2020). "While both BRCA1- and BRCA2-deficient breast cancers shared similar genomic features, only BRCA1-, but not BRCA2-deficient breast cancers, were associated with immune signatures." (PMID 31022191, 2019). "However, it is still unclear how BRCA1 and CCND1 expression levels affect the effect of T cell activation on breast cancer patient survival." (PMID 31023256, 2019). "Tissues of mammary tumors that were spontaneously induced by IR or DMBA and had different BRCA1 expression levels showed an inverse correlation between BRCA1 and CTSS, suggesting that CTSS regulates BRCA1 stability." (PMID 30006610, 2019). "Based on the current evidence, BRCA1 and LCK metagene expression may be independent markers of breast cancer." (PMID 31715586, 2019).
breast cancer (continued). "This efficacy of BSO was not seen in BRCA1 carriers who predominantly develop ER‐ cancers, although reduction of contralateral breast cancer with tamoxifen was observed, warranting longer follow‐up in this high‐risk group." (PMID 31267556, 2019). "It is interesting that heterozygous mutations in other genes in this pathway (i.e., BRCA1, BRCA2, CHEK2, NBN, ATM) predispose to breast cancer, but a heterozygous mutation in BLM does not appear to be pathogenic for breast cancer." (PMID 31614901, 2019). "Indeed, inactivation of BRCA1, BRCA2, PALB2, FAM175A, and BARD1 are synthetic lethal with PARG depletion in MCF7 breast cancer cells due to disruption of HR-mediated DDR." (PMID 30889383, 2019). "PTEN mutant samples were significantly enriched in BRCA1-, but not BRCA2-, deficient breast cancers compared to BRCA-proficient breast cancers (P = 2.8 x 10−3 and >0.99, respectively)." (PMID 31022191, 2019). "Furthermore, transcriptional activity of BRCA1 and BRCA2 genes has been observed in multiple breast cancers (including MCF-7 cells)." (PMID 32010625, 2019). "Since CX-5461 is currently in phase I/II clinical trials in Canada for breast cancer (Clinical trial identification: NCT02719977), treatment combination studies involving BRCA1/2 mutant cell lines could be informative." (PMID 31557908, 2019). "By contrast, tumors derived from Brca1-defective BCs are histologically unlike human BRCA1 or sporadic basal-like breast cancers." (PMID 31013830, 2019). "Forty-eight breast cancer patients that met the clinical criteria for BRCA testing but had received a negative BRCA1/2 result were recruited." (PMID 31780696, 2019). "The Tyrer-Cusick model, does not predict the risk of a BRCA1 or BRCA2 mutation, but instead aims to present risk of breast cancer over time." (PMID 30832243, 2019). "Subsequently treatment with PARP inhibitors was found to result in synthetic lethality in BRCA1/2 mutant tumors and the PARP inhibitors olaparib and talazoparib are now FDA-approved as monotherapy treatments in BRCA1/2 mutant advanced breast cancer." (PMID 31320901, 2019). "This study sought to determine genetics and non-genetics specialists’ views of a proposal to mainstream BRCA1 and 2 testing in newly diagnosed breast cancer patients." (PMID 30689103, 2019). "The proportion of patients with triple negative breast cancer among those who were BRCA1/2 negative in this study was 28.9% (173/597), which is higher than that of 15.4% found in the registered data of the Japan Breast Cancer Society." (PMID 31143373, 2019). "For instance, in a meta‐analysis of 40 studies, BRCA1 promoter methylation was statistically significantly higher in breast cancers negative for both ER, PR and with a triple‐negative phenotype." (PMID 31267556, 2019). "Given that BRCA1 and BRCA2 are integral in maintaining genomic integrity, we hypothesise that the inactivation of these genes may give rise to breast cancers with such immunogenic phenotype." (PMID 31022191, 2019). "As expected, BRCA1-, but not BRCA2-, deficient breast cancers were associated with increased T cell-inflamed signature." (PMID 31022191, 2019). "A recent systematic review summarized the most promising findings of DNA methylation as a biomarker of disease, concluding that hypermethylation at BRCA1 and RASSF1A gene promoters, and hypermethylation of the body of the ATM gene were more common in breast cancer cases." (PMID 31101124, 2019).
breast cancer (continued). "Based on data in a cohort of 1088 patients with primary breast cancer, our analysis results suggested that there was a negative correlation between the BRCA1 expression and the T cell activation score." (PMID 31023256, 2019). "However, BRCA1 and BRCA2 breast cancers differed in the proportions of patients with ER‐negative disease and basal‐like subtype." (PMID 30175445, 2019). "It has also been shown that luminal progenitors can give rise to basal‐like breast cancers following oncogenic insults, irrespective of BRCA1." (PMID 31267556, 2019). "The presence of double mutations of BRCA1 and BRCA2 seems to be an extremely rare event in the general population, although not exceptional in Ashkenazi breast-cancer patients." (PMID 31336956, 2019). "Indeed, reduced BRCA1 expression induced tumor-initiating cells, EMT, and stemness in breast cancer." (PMID 31213009, 2019). "To determine these relationships in human breast cancers, we used human breast cancer tissue arrays and found inverse correlation of expression patterns of CTSS and BRCA1 within each slide, suggesting possibly targeting CTSS to BRCA1 even in human breast cancer tissues." (PMID 30006610, 2019). "This contributes to hyperactivation of the Akt pathway observed in breast cancer cells lacking BRCA1 expression." (PMID 31771139, 2019). "The incidence of BRCA1 methylation is lower (5-25%) among breast cancers that are not basal-like, consistent with the subtype skewness seen for BRCA1 mutation carriers." (PMID 31225507, 2019). "Moreover, resveratrol displayed a cancer preventative role by recruiting DNMT1 to the BRCA1 promoter and enhancing MCF-7 breast cancer cell silencing." (PMID 31505792, 2019). "To conclude, our study has provided evidence that BRCA1/2 LGRs contribute significantly to the development of HBOC in Chinese mainland population and LGRs screening should be taken into consideration in hereditary breast cancer consulting." (PMID 31174498, 2019). "BRCA1 and RAD51 are classical proteins involved in double-strand break repair through homologous recombination and both proteins have high clinical relevance for breast cancer." (PMID 30939818, 2019). "The incorporation of metrics such as status of BRCA1, RICTOR, and activation of mTORC2 could guide patient selection for personalized therapies that may significantly increase the survival of breast cancer patients." (PMID 31771139, 2019). "For example, serum levels of zinc were examined among BRCA1 carriers and non-carriers and a positive impact was found such that both groups with high serum levels of zinc had a lower incidence of breast cancer." (PMID 31505792, 2019). "In addition, we demonstrated that the expression levels of BRCA1 and BRCA2 were reduced in breast cancer tissue in comparison to the healthy controls (for both P = 0.0013)." (PMID 30642295, 2019). "Actually, RARB, BRCA1, and RASSF1A are genes frequently methylated in breast cancer." (PMID 31323834, 2019). "The BRCA1 (OMIM accession number 113705) and BRCA2 (OMIM accession number 600185) (BRCA1/2) genes are the earliest discovered and most studied genes that are related to breast cancer." (PMID 30968603, 2019). "Furthermore, 30 μM resveratrol treatment of breast cancer cell lines MCF7, MDA-MB 231, and HBL 100 for two days resulted in an observed surge in BRCA1 and BRCA2 mRNA." (PMID 31505792, 2019).